PTH (parathyroid hormone)
Diseases named in the same sentence as PTH in open-access papers (continued):
Sharing a sentence is not in itself a finding about the gene and the disease.
hyperthyroidism (33 papers, 2010 to 2025). Overactivity of the thyroid gland resulting in overproduction of thyroid hormone and increased metabolic rate. "In this report, we presented a case of hyperthyroidism associated hypercalcemic crisis and reviewed the effect of thyroid hormone on metabolism of calcium, phosphate, parathyroid hormone (PTH), and 1,25-OH2-D3." (PMID 28121960, 2017). "In our study PTH levels during hyperthyroidism, that is, state associated with high FT3, were significantly lower than after treatment." (PMID 26366174, 2015). "Another cause of elevated PTH is primary or secondary hyperthyroidism." (PMID 21849030, 2011). "Exogenous TGFβ inhibits proliferation and parathyroid hormone (PTH) secretion in parathyroid cells derived from individuals with secondary hyperthyroidism." (PMID 39336822, 2024). "Renal impairment, hemoconcentration, inadequate Ca2+ intake, muscle wasting, hyperthyroidism, and low 25(OH)D3 trigger elevations in PTH to maintain Ca2+ levels." (PMID 36556486, 2022). "In one of the routine checks of hyperthyroidism in October 2018, her serum PTH was 123.6 pg/ml (normal reference range less than 88 pg/ml)." (PMID 34022862, 2021). "A 54-year-old Chinese female came to our hospital because of hyperthyroidism and persistent hyperkalemia as well as an elevated PTH level in October 2018." (PMID 34022862, 2021). "In order to further elucidate the mechanism of that phenomenon we measured PTH, calcium, and markers of bone metabolism in blood samples taken from the patients before and during treatment of hyperthyroidism." (PMID 26366174, 2015). "Decreased PTH concentrations in subjects with hyperthyroidism were also reported, followed by an increase during treatment of hyperthyroidism." (PMID 26366174, 2015). "Serum sclerostin, PTH, calcium, and bone markers [osteocalcin (OC) and collagen type I cross-linked C-telopeptide I (CTX)] were measured at diagnosis of hyperthyroidism and after treatment with thiamazole." (PMID 26366174, 2015). "The aim of the study was to investigate the relationship between parathyroid hormone (PTH) and markers of bone metabolism and changes of sclerostin concentrations before and after treatment of hyperthyroidism." (PMID 26366174, 2015). "Successful treatment of hyperthyroidism results in a significant decrease in serum sclerostin and bone markers concentrations, accompanied by an increase of PTH." (PMID 26366174, 2015). "Besides, a more potent long-acting peptide LA-PTH than PTH has also been developed as a potential drug for the treatment of hyperthyroidism by producing sustained calcemic responses." (PMID 36271004, 2022). "We hypothesized that decrease in sclerostin levels in patients recovering from hyperthyroidism might be mediated by PTH." (PMID 26366174, 2015). "Some studies suggest that vitamin D supplementation, especially calcidiol, is not effective in CKD patients with hyperthyroidism due to the interacting of the medication cinacalcet, which reduces the parathyroid hormone (PTH)." (PMID 36431017, 2022). "In parallel, the well established negative calcium balance in hyperthyroidism also improved with a decrease in serum calcium and urinary calcium excretion and an increase in PTH during ATD." (PMID 20807449, 2010). "Therefore, it may not extend to secondary hyperthyroidism which does not have elevated PTH levels." (PMID 39284277, 2024).
thyroid (33 papers, 2013 to 2026). "Parathyroid (PTH) exploration surgery carries the risk of developing post-operative thyroiditis due to vigorous manual manipulation of the thyroid gland during surgery." (PMID 26347710, 2015). "Preoperative thyroid function, parathyroid hormone (PTH), calcitonin, serum calcium, and phosphorus levels were all within normal ranges." (PMID 41476594, 2025). "In this case, the diagnosis was supported by markedly elevated calcium and PTH levels, skeletal involvement, and imaging findings consistent with thyroid invasion." (PMID 41293386, 2025). "Of these patients, 8, including 3 patients with high serum PTH levels, underwent cystectomy alone, and the remaining patients also underwent thyroidectomy for other thyroid-related conditions." (PMID 29409478, 2018). "L-thyroxine treatment increased 25-hydroxyvitamin D and reduced PTH levels only in hypothyroid women with post-partum thyroiditis." (PMID 28092021, 2017). "The primary results of our study showed that patients who had thyroid resection with the assistance of the Burjeel protocol for intraoperative ICG-near-infrared technology had greater levels of parathyroid hormone on the first day after surgery compared to the standard group." (PMID 40426871, 2025). "The prevalence of men, patients with concomitant thyroid disorders, patients with symptoms concerning bone involvement, abdominal, cardiovascular and neurological symptoms, and values of pre-operative intact PTH and albumin-corrected calcium were higher in the PC group than in the APT one." (PMID 37834940, 2023). "Thyroid nodule elastography indices were correlated positively and strongly with the presence of malignancy (r=0.729, p<0.0001), weakly with parathyroid lesion elasticity (r=0.208, p=0.0142) and PTH (r=0.357, p=0.0007)." (PMID 37588988, 2023). "Vitamin D3 injection may be helpful in situations where PTH levels may be decreased postoperatively, such as in thyroiditis, extensive lymph nodes metastasis at level VI, Graves' disease, history of previous neck operation, and extensive surgical resection." (PMID 33628238, 2021). "Though some changes to PTH may be the result of metastatic invasion of the parathyroid by thyroid carcinoma, the evidence available shows that the role of PTH in thyroid malignancy overall warrants further investigation." (PMID 28117295, 2017). "Serum Ca, parathyroid hormone (PTH), and 1,25(OH)2D levels were measured in 82 patients with thyroid disease before and after surgery." (PMID 38803480, 2024). "To evaluate the role of thyroid pathology (MNG, TC and TG) on PTH levels, we performed a one-way ANOVA test." (PMID 34574074, 2021). "PTH assay in FNA specimen and immunohistochemical study can definitely distinguish between parathyroid and thyroid lesions." (PMID 25177504, 2014). "Patients with thyroid PGLs tend to be euthyroid and serum antibodies for antithyroglobulin, antiperoxidase, and parathyroid hormone are usually negative." (PMID 41179710, 2025). "IHC staining of the tumor in the neck showed diffuse expression of PAX8 and TTF1, indicating thyroid origin, and negative staining for thyroglobulin, calcitonin, PTH, and GATA3, which support a diagnosis of an oncocytic poorly differentiated thyroid carcinoma." (PMID 40277780, 2025). "Serum levels of 25-hydroxyvitamin D were lower and PTH levels were higher in patients with post-partum thyroiditis than in patients without thyroid autoimmunity." (PMID 28092021, 2017). "The following data were collected: sex; age; type of thyroid disease; pre-operative symptoms due to thyroid pathology; surgical procedures; post-operative complications; histopathological diagnosis; and post-operative blood levels of TSH, PTH, vitamin D, and calcium." (PMID 40002845, 2025). "In addition, PTH-WO was negative in all 30 thyroid lesions considered as negative controls and were comparable with the PTH-WO-negative group (p = 0.24)." (PMID 37745742, 2023).
thyroid (continued). "Several studies also investigated other factors that may affect the accuracy, such as goiter, thyroiditis, and parathyroid hormone level; however, a separate analysis could not be performed due to insufficient available data." (PMID 27086309, 2016).
thyroid cancer (31 papers, 2010 to 2026). "This research aimed to evaluate the risk factors associated with low PTH levels following thyroid cancer surgery." (PMID 38646308, 2024). "Lower preoperative serum parathyroid hormone (PTH) levels are a potential risk factor for thyroid cancer in PHPT patients." (PMID 38202152, 2023). "The article stressed the need for deeper exploration into PTH’s role in thyroid cancer risk in PHPT patients." (PMID 38202152, 2023). "Risk Factors: Lower serum parathyroid hormone (PTH) levels seem to correlate with the presence of thyroid cancer in PHPT patients, indicating a potential risk factor for the coexistence of these conditions." (PMID 38202152, 2023). "Intriguingly, findings highlight lower serum PTH levels correlating with thyroid cancer in PHPT patients, suggesting a potential risk factor." (PMID 38202152, 2023). "Lower serum PTH levels correlated significantly with thyroid cancer presence, indicating a potential risk factor." (PMID 38202152, 2023). "Bilateral lymph node dissection, parathyroidectomy and the decrease of PTH level are the risk factors for EH in patients with thyroid cancer after operation." (PMID 35722535, 2022). "Bilateral lymph node dissection, parathyroidectomy and PTH decrease are the risk factors for postoperative EH in patients with thyroid cancer." (PMID 35722535, 2022). "Such an association provides evidence to support the role of PTH dysregulation in thyroid carcinoma." (PMID 28117295, 2017). "Thus, predictors including BRAFV600E gene mutation, Lymph#, Neu#, RDW, PLT, NLR, PLR, ALP, PTH, and clinical characters of patients were enrolled and the ML algorithm was used to predict benign and malignant thyroid tumors in our study." (PMID 36187616, 2022). "This clinicopathological risk factor combined with more specific cut-offs for intact PTH, based on the serum calcium levels measured 1 hour after surgery, may help thyroid cancer patients who undergo a total thyroidectomy with CCND to be discharged more safely." (PMID 25691901, 2015). "Carbon nanoparticle (CNP) suspensions enhanced lymph node detection sensitivity and preserved parathyroid hormone in thyroid cancer and nearly doubled sensitivity to micrometastatic lymph nodes in gastric cancer." (PMID 41246698, 2025). "The most common decrease in PTH levels affected patients operated on for thyroid cancer, at 18.18%." (PMID 37626794, 2023). "PTH may also contribute to the development of thyroid carcinoma through chromosomal rearrangement with PAD1." (PMID 28117295, 2017). "However, there is evidence to suggest a possible link between PTH and the development of thyroid carcinoma." (PMID 28117295, 2017). "Although thyroid cancer or lymph nodes can also increase the MIBI uptake and delay the MIBI washout, the serum PTH and other indices related to CRF in patients with thyroid cancer or enlarged lymph nodes in thyroids cannot be significantly relatedly elevated." (PMID 36157459, 2022). "To further clarify the influencing factors of postoperative POH and PTH restoration in patients undergoing TTIPA, we reviewed the data of thyroid cancer patients who underwent TTIPA by the same experienced physicians from June 2020 to June 2021 in our department." (PMID 35937810, 2022). "Addressing the role of PTH in thyroid cancer development, this study suggests PTH may not directly contribute." (PMID 38202152, 2023).
COVID-19 (30 papers, 2020 to 2025). A disease caused by infection with severe acute respiratory syndrome coronavirus 2. "Changes in calcium levels in COVID-19 patients may be due to alterations in intestinal absorption, imbalance in regulatory mechanism involving parathyroid hormone and vitamin D, or to a direct effect caused by SARS- CoV-2." (PMID 33080571, 2020). "Prior studies proposed several possible mechanisms for the reduced compensatory PTH response seen in patients with COVID-19." (PMID 39355148, 2024). "Firstly, the pro-inflammatory cytokines in COVID-19 patients inhibit parathyroid hormone (PTH) secretion, and the resulting impaired response to PTH causes an imbalance of calcium levels." (PMID 35678023, 2022). "Our study showed that in hospitalized COVID-19 patients, serum PTH level had a weak positive but significant correlation with D-dimer, ferritin, and LDH but not with severity, mortality, or other clinical outcomes." (PMID 33737631, 2021). "“A total of 109 patients were included in the analysis eight weeks after the onset of COVID-19, a high proportion of patients presented with impaired vitamin D metabolism and elevated parathyroid hormone (PTH) levels." (PMID 36943801, 2021). "Nevertheless, the high proportion of patients with elevated PTH concentrations, especially in severe COVID-19 cases during the recovery phase, is remarkable." (PMID 32932831, 2020). "This prospective observational cohort study reveals first evidence of a disturbed PTH–VITD axis in patients with a more severe course of COVID-19." (PMID 32932831, 2020). "Thirdly, there was still a lack of information on several elements in the complex interplay linking serum phosphate level and mortality such as Corona Virus Disease 2019 (COVID-19) and phosphate-regulating hormones including parathyroid hormone (PTH) and fibroblast growth factor-23 (FGF-23)." (PMID 39026252, 2024). "Colostrum samples showed higher levels of OPG, SOST, and PTH in the COVID-19 group, a fact that could have noteworthy implications for energy metabolism, fetal skeletal development, and postnatal bone density and mineralization." (PMID 38610889, 2024). "The assignment of logistic regression was shown in and Appendix A, Table A1.The results showed that monthly incomes, vascular access pattern, feeling of pain (within a week), age ≥ 50 years, worried about being infected by COVID-19, Hb, and PTH were influencing factors of anxiety (p < 0.05)." (PMID 37046867, 2023). "Moreover, a hypothesis has also been previously reported of a suboptimal compensatory PTH response secondary to the induced parathyroid gland alteration in COVID-19 patients." (PMID 38610889, 2024). "Therefore, this increase in PTH levels, as recorded in the colostrum of mothers who suffered COVID-19, could also affect the neonate’s bone turnover process." (PMID 38610889, 2024). "Eight weeks after the onset of COVID-19, a high proportion of patients presented with impaired VITD metabolism and elevated parathyroid hormone (PTH) levels." (PMID 32932831, 2020). "Therefore, the long-term follow-up protocol of care of COVID-19 survivors with T2D should include BMI, mean ABP, HBA1c, BUN, serum creatinine, eGFR, serum albumin, lipid profile, intact PTH, vitamin D3, ALP, serum calcium." (PMID 37312131, 2023). "In our study, PTH levels of COVID-19 cases who did not receive vitamin D supplementation were relatively high." (PMID 34836309, 2021). "Compared with the non-infected hemodialysis patients, patients with COVID-19 had a significantly shorter dialysis age, lower level of plasma albumin, the higher level of blood creatinine, potassium, and parathyroid hormone (all p < .05)." (PMID 32924707, 2020). "PTH levels of COVID-19 cases who did not receive vitamin D supplementation were relatively high; moreover, this level came close to healthy individuals in COVID-19 cases on the 14th day of vitamin D supplementation." (PMID 34836309, 2021).
COVID-19 (continued). "Interestingly, in a study by Sun and colleagues of calcium, parathyroid hormone (PTH), and vitamin D concentrations, lowered serum calcium levels led to increased organ injury and septic shock and worsened 28-day mortality in patients (n = 241) with COVID-19." (PMID 34829418, 2021). "Considering the PTH level, it was observed that, although the PTH levels of COVID-19 cases that did not receive vitamin D supplementation were relatively high, this level came close to healthy individuals in COVID-19 cases on the 14th day of vitamin D supplementation." (PMID 34836309, 2021). "Recent data on impaired compensatory PTH response in hypocalcemic patients with COVID-19, obtained by other research groups, support this hypothesis and may be due to negative feedback from 1,25(OH)2D3, although in our cohort, PTH levels were similar to the reference group." (PMID 35893730, 2022).
sarcoidosis (30 papers, 2008 to 2026). Sarcoidosis is a multisystemic disorder of unknown cause characterized by the formation of immune granulomas in involved organs. "Notably, elevated calcium levels in sarcoidosis are non-PTH-dependent, and the underlying pathogenetic mechanism is mainly correlated with granuloma-associated factors." (PMID 40520830, 2025). "A low PTH may be indicative of underlying malignancy or vitamin D intoxication, high ingestion of calcium supplements or sarcoidosis." (PMID 36547749, 2022). "This case underscores the importance of regularly monitoring calcium, phosphate, and PTH levels in sarcoidosis patients, especially when unexpected biochemical abnormalities are present." (PMID 39416579, 2024). "Regular monitoring of serum calcium, phosphate, PTH levels, and vitamin D metabolites is essential in patients with sarcoidosis, especially those presenting with signs of calcium dysregulation." (PMID 39416579, 2024). "Serum levels of creatinine and PTH were slightly higher in patients affected by sarcoidosis with respect to healthy controls (p < 0.05)." (PMID 36465894, 2022). "Since 1960's, altered calcitriol production, parathyroid hormone (PTH) activity and sensitivity to Vitamin D have been described in sarcoidosis." (PMID 33195314, 2020). "Patients on medications able to influence serum calcium and PTH (thiazides n = 3, calcium n = 2), with previously known pHPT (n = 1) and a differential diagnosis (n = 1, sarcoidosis), were excluded." (PMID 29532143, 2018). "Parathyroid hormone (PTH) was suppressed, and angiotensin-converting enzyme (ACE) was elevated, raising the suspicion of sarcoidosis." (PMID 39677199, 2024). "Herein, we have described the case of a patient who presented with high serum calcium, a normal PTH level, and histopathological evidence of active granulomatous disease, indicating the presence of both PHPT and sarcoidosis." (PMID 37799241, 2023). "Altered calcitriol production, parathyroid hormone (PTH) activity and sensitivity to vitamin D have been described in sarcoidosis." (PMID 34947932, 2021). "This case suggests that sarcoidosis can induce the synthesis of 1,25-dihydroxyvitamin D independent of PTH, potentially through the action of sarcoid granulomas." (PMID 39416579, 2024). "Sarcoidosis patients with MOF had serum levels of creatinine, 1,25OHVitD and serum PTH slightly higher with respect to those without MOF (p < 0.05)." (PMID 37924469, 2023).
Hypokalemia (28 papers, 2014 to 2026). An abnormally decreased potassium concentration in the blood. "Laboratory investigations showed increased serum creatinine with an estimated GFR 51 mL/min/1.73 m2, hypokalemia, elevated PTH levels, intermittent metabolic alkalosis, and normal blood calcium, sodium, magnesium, and phosphorus concentrations." (PMID 40428323, 2025). "In this case, a reduction in its expression was also observed in both KO models and in PTH-induced endocytosis in the Jentsch model and could also explain the cases of metabolic alkalosis and hypokalemia in patients with DD-1." (PMID 39125679, 2024). "In contrast, serum calcium, parathyroid hormone (PTH), 25-hydroxyvitamin D levels, and calciuria are usually in the normal age-related range and patients show isolated renal phosphate wasting, i.e., no other features of renal Fanconi syndrome like glucosuria, aminoaciduria, or hypokalemia." (PMID 40295317, 2025).